NOTCH3 (notch receptor 3)
Diseases named in the same sentence as NOTCH3 in open-access papers (continued):
Sharing a sentence is not in itself a finding about the gene and the disease.
CADASIL (continued). "NOTCH3 mutations result in cerebral autosomal dominant arteriopathy with subcortical infarcts and leukoencephalopathy (CADASIL), the most common inherited cerebral small vessel disease." (PMID 36470429, 2023). "CADASIL is a rare autosomal dominant disorder due to loss‐of‐function NOTCH3 variants leading to accumulation of abnormal transmembrane deposits on vascular smooth muscle cells and impaired vascular function." (PMID 37476306, 2023). "Cerebral autosomal-dominant arteriopathy with subcortical infarcts and leukoencephalopathy (CADASIL) is the most common form of hereditary cerebral small vessel disease (CSVD) in adults bearing with NOTCH3 mutation." (PMID 37684694, 2023). "Cerebral autosomal dominant arteriopathy with subcortical infarcts and leukoencephalopathy (CADASIL) is a common pure form of subcortical vascular dementia, which is caused by NOTCH3 gene mutation." (PMID 36165325, 2022). "Cerebral autosomal dominant arteriopathy with subcortical infarcts and leukoencephalopathy (CADASIL), caused by mutations in NOTCH3, is the most common cause of hereditary cerebral small vessel disease." (PMID 35617208, 2022). "Cerebral autosomal dominant arteriopathy with subcortical infarcts and leukoencephalopathy (CADASIL) is a hereditary cerebral small-vessel disease caused by mutations in the NOTCH3 gene." (PMID 36232798, 2022). "This disease is caused by a genetic mutation in the neurogenic locus notch homolog protein 3 (NOTCH3) gene, inherited as an autosomal dominant trait, the presence of which confirms the diagnosis of CADASIL." (PMID 35782589, 2022). "Cerebral autosomal dominant arteriopathy with subcortical infarcts and leukoencephalopathy (CADASIL) is caused by a cysteine-altering variant in 1 of the 34 epidermal growth factor-like repeat (EGFR) domains of the NOTCH3 protein." (PMID 35641310, 2022). "Cerebral autosomal dominant arteriopathy with subcortical infarcts and leukoencephalopathy (CADASIL) is a hereditary cerebral small-vessel disease caused by mutations in the NOTCH3 gene located on chromosome 19p13.12." (PMID 36232798, 2022). "The diagnosis of CADASIL is confirmed by the presence of NOTCH3 gene mutations or the presence of granular osmiophilic material seen with electron microscopy in arteriolar media within tissue biopsies." (PMID 36324408, 2022). "Cerebral autosomal dominant arteriopathy with subcortical infarcts and leukoencephalopathy (CADASIL), caused by NOTCH3 gene mutation, is the most prevalent monogenic cSVD." (PMID 34415564, 2022). "Cerebral autosomal dominant arteriopathy with subcortical infarcts and leukoencephalopathy (CADASIL) is an inherited arteriopathy typically caused by mutations in the NOTCH-3 gene." (PMID 36180846, 2022). "Cerebral autosomal dominant arteriopathy with subcortical infarcts and leukoencephalopathy (CADASIL) is the most common genetic disorder among those responsible for hereditary strokes, and it is caused by a mutation in the NOTCH3 gene on chromosome 19." (PMID 36142458, 2022). "Mutations in NOTCH3 which alter cysteines within exons 2–24 encompassing the epidermal growth factor-like repeats (EGFRs) were originally identified as causal in CADASIL patients." (PMID 36175824, 2022). "Mutations in NOTCH3 have been shown to cause cerebral autosomal dominant arteriopathy with subcortical infarcts and leukoencephalopathy (CADASIL), the most common form of hereditary stroke." (PMID 36107978, 2022). "From the description above, it is notable that the new NOTCH3 mutation reported here is correlated with an atypical presentation of CADASIL." (PMID 35363195, 2022). "Recent studies have discussed more about the role of cysteine‐sparing mutations of NOTCH3 in CADASIL pathogenesis since patients carrying those mutations presented typical CADASIL symptoms." (PMID 35822697, 2022). "This suggests that the heritability of Notch 3 mutation increases the risk for ischemic stroke from small vessel diseases, such as CADASIL." (PMID 35326259, 2022).
CADASIL (continued). "Cerebral autosomal dominant arteriopathy with subcortical infarcts and leukoencephalopathy (CADASIL) is the most common form of familial cerebral small vessel disease in adults, and is caused by NOTCH3 mutations." (PMID 35363195, 2022). "If true, this implicates reduction of NOTCH3 (harboring mutations that render it more likely to be trans-reduced) as an early step in the pathogenesis of CADASIL." (PMID 35409031, 2022). "The most commonly inherited SVD, CADASIL, is caused by dominantly acting cysteine-altering mutations in NOTCH3." (PMID 35393494, 2022). "The most well-known hereditary form of SVD is cerebral autosomal dominant arteriopathy with subcortical infarcts and leukoencephalopathy (CADASIL), which is caused by mutations in the NOTCH3 gene." (PMID 35223989, 2022). "The most common form of hereditary small vessel disease is CADASIL which is caused by autosomal dominant mutations of the Notch3 gene on chromosome 19p13 that either create or eliminate cysteine residues." (PMID 36324408, 2022). "Cerebral autosomal-dominant arteriopathy with subcortical infarcts and leukoencephalopathy (CADASIL) is the most common form of hereditary brain small-vessel disease characterized by NOTCH3 gene mutations." (PMID 36139821, 2022). "NOTCH3 is directly linked to cerebral autosomal dominant arteriopathy with subcortical infarcts and leukoencephalopathy also known as CADASIL." (PMID 34566624, 2021). "Genetic mutations in NOTCH3 are also associated with the autosomal dominant disorder CADASIL (cerebral autosomal dominant arteriopathy with subcortical infarcts and leukoencephalopathy) syndrome." (PMID 33750945, 2021). "Cerebral autosomal dominant arteriopathy with subcortical infarcts and leukoencephalopathy (CADASIL) is a monogenic disease caused by NOTCH3 mutations and characterized by typical clinical, neuroradiological, and pathological features." (PMID 33464533, 2021). "Dominant mutations in NOTCH3 cause CADASIL, a small vessel disease of the brain that manifests in mid-adulthood with leukoencephalopathy and subcortical ischemic events, progressively leading to disability, cognitive decline and premature death (MIM#125,310)." (PMID 32980981, 2021). "CADASIL results from stereotyped mutations in the NOTCH3 gene, which initiate a cascade of molecular events resulting in impaired vascular function." (PMID 34000009, 2021). "Although these three patients with SS and a NOTCH3 null mutation exhibit clinical and neuroimaging features that share similarities with those observed in CADASIL patients, we believe that this genetic form of SS and CADASIL are two distinct entities." (PMID 32980981, 2021). "Cerebrovascular pathology at the biochemical level has been informed by the study of cerebral autosomal dominant arteriopathy with subcortical infarcts and leukoencephalopathy (CADASIL), a vascular disorder caused by NOTCH3 mutations." (PMID 34446744, 2021). "Mutations in NOTCH3 can lead to cerebral autosomal dominant arteriopathy with subcortical infarcts and leukoencephalopathy (CADASIL), the most frequent hereditary cerebral small vessel disease characterized by dementia and stroke." (PMID 34551193, 2021). "Notch3 mutations are perhaps most well-known in cerebral autosomal dominant arteriopathy with sub-cortical infarcts and leukoencephalopathy (CADASIL)." (PMID 33800271, 2021). "CADASIL is a small vessel disease caused by mutations in NOTCH3 that lead to an odd number of cysteines in the EGF-like repeat domain, causing protein misfolding and aggregation." (PMID 33767277, 2021). "Nevertheless, a recent study investigating NOTCH3 variants in 261 Chinese patients with clinically suspected CADASIL showed that p.R607C and p.R544C were the first and second most common variants, respectively." (PMID 33942994, 2021). "In conclusion, we exhibited a distinct spectrum of NOTCH3 variants in Chinese CADASIL patients and intrigued a potential genotype-phenotype correlation." (PMID 34335700, 2021).
CADASIL (continued). "Cerebral autosomal dominant arteriopathy with subcortical infarcts and leukoencephalopathy (CADASIL) is a monogenic disease caused by NOTCH3 mutations." (PMID 33464533, 2021). "Cerebral autosomal dominant arteriopathy with subcortical infarcts and leukoencephalopathy (CADASIL) is a cerebral small vessel disease caused by mutations in the NOTCH3 gene." (PMID 31915071, 2020). "Mutations of Notch3 are associated with a dominantly inherited disease CADASIL (cerebral autosomal-dominant arteriopathy with subcortical infarcts and leukoencephalopathy), and there is further evidence linking Notch3 misregulation to hypertensive disease." (PMID 32210034, 2020). "Cerebral autosomal-dominant arteriopathy with subcortical infarcts and leukoencephalopathy (CADASIL) is a hereditary disease resulting from mutations of the NOTCH3 gene." (PMID 33101365, 2020). "Cerebral autosomal dominant arteriopathy with subcortical infarct and leukoencephalopathy (CADASIL) is a Notch3 mutation-induced cerebral small vessel disease, leading to recurrent ischemic stroke and vascular dementia." (PMID 33511138, 2020). "Cerebral autosomal dominant arteriopathy with subcortical infarcts and leukoencephalopathy (CADASIL) is an inherited small vessel disease caused by mutations in NOTCH3 gene with remarkable phenotypic heterogeneity." (PMID 32122318, 2020). "Although CADASIL is generally caused by heterozygous mutations in NOTCH3, several CADASIL cases involving homozygous mutations have been reported." (PMID 32457593, 2020). "Cases of CADASIL associated with homozygous NOTCH3 mutations are rare and subsequently understudied." (PMID 32122318, 2020). "Assuming that CADASIL is underdiagnosed in some cases of lacunar infarction, this study was designed to examine the prevalence of NOTCH3 gene mutations in the patients at highest risk who were admitted for lacunar infarctions." (PMID 32477100, 2020). "Here, we report the first patients of CADASIL from a Chinese family with homozygous NOTCH3 mutation c.1759C > T (p.R587C), and pathological analysis confirm GOM deposits in the vessel walls in proband patient." (PMID 32122318, 2020). "CADASIL is a cerebral small vessel disease affecting the vascular smooth muscle cells (VSCMs) and characterised by NOTCH3 mutations and/or the presence of granular osmiophilic material (GOM)." (PMID 31915071, 2020). "CADASIL is caused by pathogenic mutations in NOTCH3 gene on chromosome 19p13, transmitted in families in an autosomal dominant manner with variable penetrance." (PMID 32231578, 2020). "Recently, it has been reported that some patients with NOTCH3 gene mutations show atypical clinical symptoms of CADASIL." (PMID 32477100, 2020). "Typical cerebral autosomal-dominant arteriopathy with subcortical infarcts and leukoencephalopathy (CADASIL) is caused by mutations in the human NOTCH3 gene." (PMID 33101365, 2020). "In the case of a Notch3 mutation, if any of the 6 Cys is mutated into another amino acid, it leads to a rare neurodegenerative syndrome, called CADASIL (Cerebral Autosomal Dominant Arteriopathy with Subcortical Infarcts and Leukoencephalopathy)." (PMID 33194454, 2020). "Background and Objectives: Previous studies found differences in the characteristics of NOTCH3 mutations in Caucasians and Asians with cerebral autosomal dominant arteriopathy with subcortical infarcts and leukoencephalopathy (CADASIL)." (PMID 31443546, 2019). "Cerebral autosomal dominant arteriopathy with subcortical infarcts and leukoencephalopathy (CADASIL) is a rare hereditary cerebrovascular disease caused by a NOTCH3 mutation." (PMID 30778920, 2019). "CADASIL is caused by mutations in the NOTCH3 gene and is characterized by vasculopathy in perforator cerebral arteries secondary to fibrosis and accumulation of osmiophilic substances." (PMID 31142262, 2019). "There are 170 missense mutations known to cause CADASIL, in which 95% of them are identified in the NOTCH3 gene." (PMID 31288479, 2019).
CADASIL (continued). "It is noteworthy that these types of NOTCH3 mutations occurred in the majority of Korean CADASIL patients." (PMID 31443546, 2019). "Although CADASIL manifests clinically as a vascular disease of the brain, all small- and medium-sized arteries are likely affected by CADASIL-causing NOTCH3 mutations." (PMID 31647781, 2019). "Mutations in the NOTCH3 gene have been reported to be causally associated with cerebral autosomal-dominant arteriopathy with subcortical infarcts and leukoencephalopathy (CADASIL)." (PMID 31288479, 2019). "Cerebral autosomal dominant arteriopathy with subcortical infarcts and leukoencephalopathy (CADASIL) is a rare hereditary disease caused by mutations in the NOTCH3 gene, which encodes for the first five epidermal growth factor repeats on chromosome 19p13.12." (PMID 31443546, 2019). "Cerebral autosomal dominant arteriopathy with subcortical infarcts and leukoencephalopathy (CADASIL) is a hereditary arteriopathy associated with the NOTCH3 gene." (PMID 31146726, 2019). "We provide direct evidence that CADASIL-causing NOTCH3 mutations have vascular manifestations beyond the cerebral vasculature and that peripheral small arteries are abnormal in CADASIL." (PMID 31647781, 2019). "Cerebral autosomal dominant arteriopathy with subcortical infarcts and leukoencephalopathy (CADASIL) is a hereditary vascular small-vessel disease caused by Notch3 mutations and represents the most common form of hereditary stroke disorder." (PMID 29802397, 2018). "Data on the role of Notch in human vasculature are limited, but patients with CADASIL are known to have missense mutations in Notch3 or Jag131." (PMID 30573741, 2018). "Cerebral autosomal dominant arteriopathy with subcortical infarcts and leukoencephalopathy (CADASIL) is a hereditary vascular small-vessel disease caused by Notch3 mutations." (PMID 29802397, 2018). "The mutation of NOTCH3 causes cerebral autosomal dominant arteriopathy with subcortical infarcts and leukoencephalopathy (CADASIL), a disease related to stroke and dementia, due to the degeneration of vSMCs." (PMID 28298363, 2017). "CADASIL is caused by a mutation in the NOTCH3 gene, which leads to an accumulation of the extracellular domain of NOTCH3 (NOTCH3ECD) in the basement membrane around cerebral blood vessels." (PMID 28202749, 2017). "Cerebral autosomal dominant arteriopathy with subcortical infarcts and leukoencephalopathy (CADASIL) is the most common form of hereditary stroke disorder caused by mutations in the NOTCH3 gene." (PMID 27206574, 2016). "Cerebral autosomal dominant arteriopathy with subcortical infarcts and leukoencephalopathy (CADASIL) is a dominantly hereditary small-vessel disease caused by mutations of the NOTCH3 gene in 19p13." (PMID 27206574, 2016). "Cerebral autosomal dominant arteriopathy with subcortical infarcts and leukoencephalopathy (CADASIL) is a rare hereditary stroke caused by mutations in NOTCH3 gene." (PMID 26270344, 2015). "Cerebral autosomal dominant arteriopathy with subcortical infarcts and leukoencephalopathy (CADASIL), caused by mutations in the NOTCH3 gene, is the most common monogenic disorder causing lacunar stroke and cerebral small vessel disease (SVD)." (PMID 26305465, 2015). "Cerebral autosomal dominant arteriopathy with subcortical infarcts and leukoencephalopathy (CADASIL) is the most common heritable form of vascular dementia in adults and is caused by mutations in the NOTCH3 gene." (PMID 26435852, 2015). "The most common of these is cerebral autosomal dominant arteriopathy with subcortical infarcts and leukoencephalopathy (CADASIL), caused by mutations in the NOTCH3 gene." (PMID 26305465, 2015). "Cerebral Autosomal Dominant Arteriopathy with Subcortical Infarcts and Leukoencephalopathy (CADASIL) is a hereditary small vessel disease caused by mutations in the NOTCH3 gene, leading to mid-adult onset stroke and dementia." (PMID 26715087, 2015).
CADASIL (continued). "Cerebral autosomal dominant arteriopathy with subcortical infarcts and leukoencephalopathy (CADASIL) is originally featured with a strong clustering of mutations in NOTCH3 exons 3–6 and leukoencephalopathy with frequent anterior temporal pole involvement." (PMID 26308724, 2015). "Cerebral autosomal dominant arteriopathy with subcortical infarcts and leukoencephalopathy (CADASIL) is the most common heritable form of vascular dementia and it is caused by mutations in the NOTCH3 gene." (PMID 26435852, 2015). "First, approximately 70% of CADASIL cases in Taiwan are resulting from the NOTCH3 R544C mutation, whereas mutations in exon 3–6 of NOTCH3 are responsible for approximately 90% of CADASIL patients in most Caucasian populations." (PMID 26308724, 2015). "Cerebral Autosomal Dominant Arteriopathy with Subcortical Infarcts and Leukoencephalopathy (CADASIL) is a hereditary disorder which affects the cerebral vasculature due to mutations in the NOTCH 3 gene." (PMID 29213994, 2015). "A single NOTCH3 mutation R544C in exon 11 accounts for the majority of CADASIL subjects in southern Korea." (PMID 26308724, 2015). "We herein described a case of a CADASIL-like disorder with a novel heterozygous missense mutation of the human NOTCH3 gene." (PMID 25834748, 2015). "CADASIL is caused by mutations in NOTCH3 and is characterized by a gradual loss of arterial mural cells and accumulation of dark deposits of granular osmiophilic material (GOM) in the basal lamina of pericytes and VSMCs7." (PMID 26563570, 2015). "Increased PFO prevalence was observed in patients with CADASIL, a condition caused by germline NOTCH3 mutations, suggesting a potential role of Notch3 in FO closure." (PMID 25215881, 2014). "NOTCH3 mutations are known to be associated with cerebral autosomal dominant arteriopathy with subcortical infarcts and leukoencephalopathy (CADASIL)." (PMID 24936512, 2014). "Cerebral autosomal dominant arteriopathy with subcortical infarcts and leukoencephalopathy (CADASIL) – is the most common genetic source of vascular dementia in adults, being caused by a mutation in NOTCH3 gene." (PMID 25009481, 2014). "Cerebral autosomal dominant arteriopathy with subcortical infarcts and leukoencephalopathy (CADASIL) is an adult onset cerebral small vessel disorder caused by the mutations of the neurogenic locus notch homolog protein 3 (NOTCH3) gene." (PMID 25098330, 2014). "Cerebral autosomal dominant arteriopathy with subcortical infarcts and leukoencephalopathy (CADASIL) is a rare hereditary disease caused by mutations in the NOTCH3 gene on chromosome 19p13.1." (PMID 24929957, 2014). "Since the clinical and MRI findings for this patient were highly suggestive of CADASIL, genetic testing for NOTCH3 mutations was performed." (PMID 24929957, 2014). "Genetic testing was performed and confirmed an Arg133Cys mutation in the NOTCH3 gene, which has been linked to CADASIL in previous reports." (PMID 25009481, 2014). "In this study, we reported a novel cysteine-sparing NOTCH3 mutation at the nucleotide position 446 (c.446G>T; p.G149V) in a Chinese family with CADASIL." (PMID 25098330, 2014). "Magnetic resonance imaging findings were very consistent with a diagnosis of CADASIL, which was confirmed by genetic testing for NOTCH3 mutations." (PMID 24929957, 2014). "Cerebral autosomal dominant arteriopathy with subcortical infarcts and leukoencephalopathy (CADASIL) is caused by NOTCH3 gene mutations that result in vascular smooth muscle cell (VSMC) degeneration." (PMID 23799017, 2013). "Mutations within the NOTCH3 gene cause cerebral autosomal dominant arteriopathy with subcortical infarcts and leukoencephalopathy (CADASIL)." (PMID 24086431, 2013). "Cerebral autosomal dominant arteriopathy with subcortical infarcts and leukoencephalopathy (CADASIL) is a genetic disorder caused by mutations in the NOTCH3 gene, which maps to chromosome 19 and encodes the transmembrane receptor NOTCH3." (PMID 23799017, 2013).